PRAMEF17 (PRAME family member 17)
Synonyms: OTTHUMG00000007909
Tractability: PROTAC: ubiquitination databases record sites on it.
Gene: Protein-coding gene on chromosome 1 (13,389,632 to 13,392,629, forward strand). Ensembl gene ENSG00000204479.
Gene Ontology:
Molecular function: ubiquitin-like ligase-substrate adaptor activity
Biological process: proteasome-mediated ubiquitin-dependent protein catabolic process; negative regulation of apoptotic process; negative regulation of cell differentiation; negative regulation of DNA-templated transcription; positive regulation of cell population proliferation
Cellular component: Cul2-RING ubiquitin ligase complex; cytoplasm
Genetic constraint (gnomAD): Loss-of-function variants: 48 observed, 37.28 expected, observed/expected ratio (o/e) 1.29, 90% interval 1.02 to 1.64. The upper end of that interval is the gene's LOEUF score, 1.64, which puts it in group 6 of 6, group 1 being the genes least tolerant of losing a copy. Missense variants: 639 observed, 571.79 expected, observed/expected ratio (o/e) 1.12, 90% interval 1.05 to 1.19. Synonymous variants: 246 observed, 223.47 expected, observed/expected ratio (o/e) 1.1, 90% interval 0.99 to 1.22.
Homologues: Orthologues: chimpanzee PRAMEF17 (95% identical), mouse Pramel12 (43% identical), rat Pramef8 (43% identical), rat Pramef5 (41% identical), mouse Pramel43 (40% identical), mouse Pramel21 (40% identical), mouse Pramel36 (40% identical), mouse Pramel46 (40% identical), mouse Pramel49 (40% identical), rat Pramef20l1 (40% identical), rat Pramel36l1 (40% identical), mouse Pramel16 (39% identical), and 79 more. Paralogues in human: PRAMEF33 (88% identical), PRAMEF10 (88% identical), PRAMEF18 (62% identical), PRAMEF19 (62% identical), PRAMEF1 (60% identical), PRAMEF14 (60% identical), PRAMEF13 (59% identical), PRAMEF2 (59% identical), PRAMEF12 (53% identical), PRAMEF8 (52% identical), PRAMEF7 (51% identical), PRAMEF20 (51% identical), and 12 more.